SNORD13D (small nucleolar RNA, C/D box 13D)
Gene: Small nucleolar RNA gene on chromosome 15 (57,278,570 to 57,278,673, reverse strand). Ensembl gene ENSG00000239035.
Gene Ontology:
Biological process: RNA processing
Cellular component: nucleolus
Homologues: Orthologues: chimpanzee SNORD13D (99% identical), macaque SNORD13D (95% identical). Paralogues in human: SNORD13E (89% identical), SNORD13 (88% identical), SNORD13P1 (86% identical), SNORD13P3 (85% identical).